IL6 (interleukin 6)
Diseases named in the same sentence as IL6 in open-access papers (continued):
Sharing a sentence is not in itself a finding about the gene and the disease.
atherosclerosis (continued). "NF-κB activation leads to the production of pro-inflammatory cytokines such as IL-6, TNF-α, and IL-1β, which drive atherosclerosis, myocardial fibrosis, and immune evasion in tumors." (PMID 40227756, 2025). "Several studies have demonstrated that hyperinsulinemia can activate pro-inflammatory pathways, leading to elevated levels of cytokines such as IL-6 and TNF-α, which further impair vascular function and promote atherosclerosis." (PMID 40265186, 2025). "These agents also suppress inflammatory pathways by reducing pro-inflammatory cytokines such as interleukin-6 (IL-6) and tumor necrosis factor-alpha (TNF-α), thus stabilizing atherosclerotic plaques and slowing atherosclerosis progression." (PMID 40807170, 2025). "Visceral adiposity secretes the pro-inflammatory cytokines interleukin-6 (IL-6) and tumor necrosis factor-α (TNF-α), reducing endothelial nitric oxide and upregulating adhesion molecules that initiate atherosclerosis." (PMID 40727914, 2025). "The KEGG path view suggests that LBP, MMP9, APOB, IL6, and RAP1B are involved in lipid metabolism and atherosclerosis." (PMID 41221287, 2025). "Pro-inflammatory cytokines, including TNF-α, COX-2, and IL-6, recruit monocytes to the vessel wall, augment ox-LDL uptake, and enhance SR expression, thereby accelerating foam cell formation and atherosclerosis." (PMID 40475061, 2025). "Overexpression of HULC can decrease the levels of IL1, IL6 and IL8, mitigate dyslipidemia, and alleviate atherosclerosis." (PMID 41300831, 2025). "While earlier works emphasized well-known inflammatory markers (e.g., IL6, TNF-α), we identified novel candidates (OAS2, TMEM106A, ABCB1) with limited prior links to atherosclerosis or stroke." (PMID 40371070, 2025). "Our study focused on pro-inflammatory cytokines, particularly IL-6, IL-2, and TNF-α, due to their involvement in the inflammatory cascade of atherosclerosis." (PMID 40265387, 2025). "Experimental results showed that the IL-6 level in the galangin-treated group decreased from 9.64 to 5.42 mg/L, and TNF-α decreased from 6.63 to 3.57 mg/L in the atherosclerosis model." (PMID 40242436, 2025). "In animal models of atherosclerosis, DPP-4is lower circulating CRP, MCP-1, IL-6, and TNF-α while raising the anti-inflammatory IL-10." (PMID 41462689, 2025). "Excess visceral fat promotes tumorigenesis through increased insulin-like growth factor-1 (IGF-1) signaling and pro-inflammatory cytokines (IL-6, TNF-α), while also accelerating atherosclerosis and heart failure." (PMID 40227756, 2025). "Migraine sufferers are more prone to developing arterial atherosclerosis, which contains eleven targets including Akt1, TNF, IL-6, etc.." (PMID 41009787, 2025). "This chronic inflammation shares key features with atherosclerosis, where elevated cytokine levels, particularly TNF-α and IL-6, promote endothelial dysfunction, a key initial step in atherosclerosis pathophysiology." (PMID 40299461, 2025). "Inflammation in PsD plays a pivotal role in exacerbating atherosclerosis and cardiometabolic diseases, with proinflammatory cytokines such as TNF, IL-1, IL-6, and IL-17 contributing to endothelial dysfunction and vascular damage." (PMID 41266905, 2025). "In the inflammatory response, the levels of inflammatory cytokines IL-1β, IL-6, and TNF-α were significantly elevated in the atherosclerosis group of rats, while paeoniflorin treatment significantly reduced the expression of these inflammatory cytokines." (PMID 40242436, 2025). "As expected, doxorubicin induced mitochondrial dysfunction, activation of NF-κB, and upregulation of proinflammatory cytokines (e.g., IL-6, IL-1β, and TNF-α) in HUVECs, triggering EndMT, a crucial process in the initiation and progression of atherosclerosis." (PMID 39851526, 2025). "Chronic H. pylori infection contributes to atherosclerosis by promoting systemic inflammation through cytokines such as TNF-α, interleukin-6 (IL-6), and interleukin-1 beta (IL-1β)." (PMID 40893911, 2025).
atherosclerosis (continued). "Inflammatory response plays an important role in the progression of atherosclerosis, and TNF-α, IL-6, and IL-1β pro-inflammatory factors tend to induce the development of AS by destroying the vascular endothelium and increasing lipid deposition." (PMID 40606622, 2025). "Chronic inflammation is also a well-defined non-traditional risk factor in the pathogenesis of atherosclerosis, where cytokines such as interleukin 1 (IL-1), interleukin 6 (IL-6), and TNF-α may promote endothelial dysfunction, which plays a key role in the process of atherogenesis." (PMID 41301765, 2025). "Cytokines, such as IL-6 and TNF-α, facilitate atherosclerosis, and vascular damage activates cells like osteoblasts and osteoclasts, further accelerating atherosclerosis as reported in some studies." (PMID 39697523, 2025). "According to our results, typical levels of SASP (TNF-α, and IL-6) in serum from atherosclerosis mice were higher, while paeonol significantly decreased TNF-α and IL-6 compared with the model group." (PMID 38202844, 2024). "Previous studies have shown that high doses of crocin proportionally reduce the levels of macrophages and their inflammatory derivatives in atherosclerosis, including MCP-1, TNF-α, IL-6, MMP-2, MMP-3, and MMP-9." (PMID 38830933, 2024). "IL-1β, IL-6, IL-17, TNF-α, and hs-CRP are involved in the pathogenesis of atherosclerosis, psoriasis, and RA." (PMID 38927529, 2024). "In atherosclerosis, oxidized low-density lipoprotein (ox-LDL) and pro-inflammatory cytokines such as Interleukin-6 (IL-6) and Tumor Necrosis Factor-alpha (TNF-α) activate immune cells contributing to foam cell formation and arterial wall thickening." (PMID 39877020, 2024). "In addition, during the course of AS, IL-6 interacts with the hypothalamic-pituitary-adrenal (HPA) axis, leading to traditional cardiovascular risk factors including decreased insulin sensitivity, increased BMI, and the occurrence of hypertension, exacerbating atherosclerosis." (PMID 38988836, 2024). "For instance, salivary cytokines such as IL-6 and TNF-α were suggested as potential markers for atherosclerosis due to their significant increase in atherosclerosis patients." (PMID 38304464, 2024). "In atherosclerosis, ox-LDL and cytokines like IL-6 and TNF-α drive foam cell formation and arterial thickening." (PMID 39877020, 2024). "This activates M1-type macrophages which produce chemokines, namely CCL2, IL6, CXCL8, CXCL2, and CXCL20, leading to a complex cascade that encourages atherosclerosis." (PMID 39634983, 2024). "The lipid and atherosclerosis pathway, for example, involves several inflammation-related targets such as AKT1, TNF, and IL6, underscoring chronic inflammation’s critical role in atherosclerosis progression." (PMID 39822742, 2024). "APG can improve atherosclerosis by stimulating apoptosis of macrophages and downregulating the secretion of cytokines (TNF-α, IL-1β, and IL-6)." (PMID 39830346, 2024). "CA also notably reduces pro-inflammatory factors such as IL-6, TNF-α, and MCP-1, regulates cholesterol metabolism, diminishes lipid plaque accumulation, and slows atherosclerosis progression." (PMID 39459158, 2024). "Pro-inflammatory cytokines, such as IL-6 and TNF-α, are elevated in both conditions and inflammation plays a significant role in the development of atherosclerosis, promoting endothelial dysfunction and plaque formation in cardiovascular disorders." (PMID 38441007, 2024). "Plaque macrophages increase the expression of proinflammatory cytokines such as IL-6, IL-1β, and TNF-α, which are the first-wave inflammatory cytokines that impact atherosclerosis substantially." (PMID 36536168, 2024). "Pro-inflammatory signaling molecules, including interleukin-1β (IL-1β), tumor necrosis factor-α (TNF-α), and interleukin-6 (IL-6), are notably elevated in both IBD and atherosclerosis." (PMID 38558708, 2024).
atherosclerosis (continued). "MIAT activation was also demonstrated to enhance angiogenesis and increase the expression of inflammatory factors (IL-1β, IL-6, and TNF-α) in mice with atherosclerosis." (PMID 39273193, 2024). "Inflammatory cytokines released by adipose tissue, such as IL-6 and TNF-alpha, promote endothelial dysfunction, atherosclerosis, and plaque instability, all of which are key factors in the development of cardiovascular disease." (PMID 39408157, 2024). "Various inflammatory stimuli such as interleukin-6 (IL-6), tumour necrosis factor-alpha (TNF-α) and intercellular adhesion molecule 1 (ICAM-1) play major roles in atherosclerosis." (PMID 39769058, 2024). "Chronic Mg deficiency leads to enhanced baseline inflammation driven by elevated cytokines like IL-6 and C-reactive protein (CRP) and therefore plays a central role in atherosclerosis." (PMID 39408157, 2024). "In atherosclerosis and coronary heart disease, an HFD elevates IL-6, C-reactive protein (CRP), and TNF-α preceding endothelial dysfunction and nitric oxide depletion." (PMID 38999835, 2024). "In response to MP/NP exposure, the body can release pro-inflammatory cytokines, such as interleukin-6 (IL-6) and tumor necrosis factor-alpha (TNF-α), which play key roles in vascular inflammation and atherosclerosis development." (PMID 39453150, 2024). "TNF- α also promotes the production of genes producing IL-6 and MCP-1, which contributes to the advancement of atherosclerosis." (PMID 38266537, 2024). "Nevertheless, the level of proinflammatory cytokines such as TNF-α, IL-1β, IL-6, and IFN-γ was also found to be elevated in several heart diseases including congestive heart failure, atherosclerosis, coronary artery disease and myocardial infarction." (PMID 38441007, 2024). "Circulating inflammatory markers such as interleukin-6 (IL-6) and C-reactive protein (CRP) are closely related with endothelial dysfunction and atherosclerosis." (PMID 37831667, 2023). "In atherosclerosis, bone marrow mesenchymal stem cells increased production of cytokines, such as TNF-α, IL-6, and IL-1, which regulated the differentiation of HSCs via affecting the hematopoietic microenvironment of bone marrow." (PMID 37525137, 2023). "In vitro results have shown that trelagliptin treatment inhibited the expression of MCP-1, CXCL-1, IL-6, VCAM-1, and ICAM-1 in human aortic endothelial cells exposed to IL-1β, mimicking the microenvironment of atherosclerosis." (PMID 37175496, 2023). "Turmeric improves serum SOD and CAT activity; inhibits the production of inflammatory molecules, such as TNF-α, IL-6, COX-2, and 5-LOX; prevents endothelial dysfunction; and suppresses cholesterol accumulation in macrophage foam cells and atherosclerosis." (PMID 37241765, 2023). "A study analysing atherosclerotic plaques in human coronary arteries showed that the cytokine IL-17 released by Th17 can synergistically increase the secretion of IL-6 with IFN-γ, promoting inflammation and atherosclerosis." (PMID 38143759, 2023). "The intricate connection between atherosclerosis markers and pro-inflammatory cytokines, such as tumor necrosis factor-alpha (TNF-α) and interleukin-6 (IL-6), is a complex and highly significant area in cardiovascular research." (PMID 37893519, 2023). "TIPE2 can accelerate the differentiation of M2 macrophages by activating the PI3K signaling pathway, significantly reduce the expression of TNF-α, IL-6, and MCP-1, and play a protective role in atherosclerosis." (PMID 37069964, 2023). "SIN mainly affected 5 target genes, NFκB-1, TNF, interleukin 6, interleukin 1β and signal transducer and activator of transcription 3, and IL-17, AGE-RAGE signaling pathways, lipids, and atherosclerosis were all controlled to achieve therapeutic effects." (PMID 38206710, 2023). "Higher levels of interleukin-6 and CRP are positively correlated with atherosclerosis in SSc patients." (PMID 38066767, 2023).
atherosclerosis (continued). "IL-17 can induce IL-6 and Matrix Metallo Proteinase (MMP) release by affecting endothelial cells, which results in reperfusion damage, thrombosis, and atherosclerosis." (PMID 37992065, 2023). "IL-6 and TNF-α are the most attributable pro-inflammatory cytokines that enhance atherosclerosis and metabolic dysregulation in obesity." (PMID 37833312, 2023). "The serum IL-1β, IL-6, and TNF-α levels were significantly reduced, whereas IL-10 was greatly increased in mice with early and advanced atherosclerosis after GLSP treatment." (PMID 36923537, 2023). "Further, it was found that patients with generalized atherosclerosis, in addition to a statistically significant increase in T-regulatory lymphocytes, TGFβ and IL7, also had a significant decrease in concentrations of IL6 and IL8." (PMID 37569579, 2023). "Our results suggest that IL-6 is useful to be a good biomarker reflecting the severity of CAD assessed by GS and to play a major role in the progression of atherosclerosis." (PMID 38017432, 2023). "In cardiovascular diseases, IL-6 and TNF are involved in the pathogenesis of atherosclerosis, myocardial infarction, and heart failure." (PMID 37047011, 2023). "Pro-inflammatory cytokines, such as IL-6, IL-1β, MCP-1 and TNF-α, are involved in the pathogenesis of atherosclerosis through inducing inflammatory cascades in the heart." (PMID 38041095, 2023). "NF-κB also regulates cellular factors, including interleukin-1 β (IL-1 β), TNF-α, interleukin 6 (IL-6), interleukin 12 (IL-12), Interferon γ (IFN γ), and indirectly involves in the low-grade inflammatory reaction in atherosclerosis." (PMID 37063954, 2023). "In an animal model of cerebrovascular illness, the implant considerably decreased the levels of serum calcineurin, Interleukin-1β (IL-1β), Interleukin-6 (IL-6), and monocyte chemoattractant protein-1 (MCP-1), offering long-lasting relief from atherosclerosis." (PMID 36986553, 2023). "Among inflammatory markers, IL6 is the main candidate to be considered as an indicator of plaque progression, whereas there is a lack of evidence concerning other cytokines and the risk of atherosclerosis progression in patients with carotid stenosis or ischemic stroke." (PMID 37762627, 2023). "LOX-1 and oxLDL are fundamental in atherosclerosis, where oxLDL/LOX1 promotes ROS generation and NF-κB activation inducing the expression of IL-6, a STAT3 activator." (PMID 36982155, 2023). "Stress hyperglycemia triggers the production of inflammatory factors such as IL-6, IL-8, and TNF-alpha in the body, which can exacerbate atherosclerosis through various intracellular pathways." (PMID 37046267, 2023). "Lutein can also decrease disease progression in patients with early atherosclerosis, since it reduces serum LDL, triglycerides, interleukin-6 (IL-6), and macrophage chemo-attractant protein-1." (PMID 37655002, 2023). "To date, anti-inflammatory therapy in atherosclerosis has targeted the NLRP3 inflammasome and upstream links of the IL-1β/IL-6/CRP axis." (PMID 36768404, 2023). "Another action is the indirect reduction of the activation of IL-1β and downstream in IL-6 and CRP, which are well-known mediators that activate macrophages and propagate atherosclerosis." (PMID 37374202, 2023). "Puerarin, also identified in Pueraria lobata, inhibits vascular smooth muscle proliferation and inflammation in atherosclerosis via lowering the expression of α-SMA and the inflammatory proteins IL-6 and IL-8." (PMID 38066464, 2023).
atherosclerosis (continued). "Further, the circulating level of resistin is positively associated with inflammatory biomarkers such as TNF-α, IL-1β, and IL-6, and diseases such as DM2 and atherosclerosis." (PMID 36788619, 2023). "Therefore, CSJD may regulate targets such as PIK3CA, AKT1, TNF, IL-6, and others through the lipid and atherosclerosis pathway, block the key pathways and molecules of lipid metabolism, and thus achieve the effect of inhibiting dengue virus replication and improving clinical symptoms of patients." (PMID 38206728, 2023). "Interleukin-6 (IL-6), interleukin-12, and interferon-gamma (IFN-γ) are a few of the several cytokines that have a role in the development of atherosclerosis." (PMID 38292957, 2023). "This review suggests that TMP inhibits inflammation in atherosclerosis by modulating TLR4, IL-6, and IL-1β levels." (PMID 35500001, 2022). "IL-6 pathway involves JAK/STAT activation and has important roles in atherosclerosis development and progression." (PMID 36362423, 2022). "Furthermore, SARS-CoV-2 leads to cytokine outburst, including IL-6, IL-1b, IL-2, IL-10, and monocyte chemoattractant protein-1 (MCP-1), which are also associated with vascular dysfunction and vascular disease such as atherosclerosis, abdominal aortic aneurysm, varicose veins and hypertension." (PMID 36211676, 2022). "As previously discussed, VAT tends to stimulate the release of cytokines (such as IL-6 and TNF-a) and hormones that can lead to systemic inflammation, thereby increasing coagulation and adhesion molecules, contributing to atherosclerosis formation." (PMID 35492380, 2022). "Senescent ECs can produce more inflammatory factors such as interleukin-1, interleukin-6, interleukin-8, interleukin-15, MCP-1, TNF, and other mediators that promote atherosclerosis and thrombosis, and express cell adhesion molecules such as ICAM-1, and PAI-1." (PMID 35642067, 2022). "The increased inflammation cytokines, including IL-6, IL-1β, and TNF-α, are also the main characteristics of atherosclerosis." (PMID 36145277, 2022). "The molecular activity prediction analysis showed that TQ inhibition of IL-6 significantly attenuated the levels of Akt, NF-kB Complex, Ap1, ERK 1⁄2 STAT5 a/b, PTGS2, PI3K Complex, XIAP, and estrogen receptor in atherosclerosis." (PMID 35723378, 2022). "A previous study has shown that inflammatory factors such as IL-6, IL-8, and hs-CRP can promote the formation of thrombosis, among which hs-CRP is an important indicator reflecting atherosclerosis and acute inflammatory response." (PMID 35265308, 2022). "The dysregulated pro-inflammatory cytokines in MS, including IL-1, IL-6, TNF-ƒÑ, or IFN-ƒ×, were thought to be involved in inducing atherosclerosis in those patients." (PMID 35147792, 2022). "Previous study showed that selective EGFR deletion in myeloid cells limited their ability to produce IL-6, TNF-α, and to uptake lipids, thereby reducing the development of atherosclerosis." (PMID 35783840, 2022). "Visceral and ectopic fat accumulation in NASH is associated with an over-secretion of FFAs and a number of adipocytokines, including TNF-a, IL-6, and PAI-1, promoting vascular inflammation and endothelial dysfunction, a marker of early atherosclerosis." (PMID 35739957, 2022). "As part of the acute phase response, IL-6 increases CRP, fibrinogen, and plasminogen activator inhibitor levels, which are closely related to atherosclerosis." (PMID 36082127, 2022). "Data obtained in table showed that, there was a significant elevation in the levels of CRP, IL-6 and TNF-α in obese with atherosclerosis patients and obese subjects compared with control group (p < 0.001)." (PMID 36407366, 2022).